KRTAP2-3 (keratin associated protein 2-3)
Description:
In the hair cortex, hair keratin intermediate filaments are embedded in an interfilamentous matrix, consisting of hair keratin-associated proteins (KRTAP), which are essential for the formation of a rigid and resistant hair shaft through their extensive disulfide bond cross-linking with abundant cysteine residues of hair keratins. The matrix proteins include the high-sulfur and high-glycine-tyrosine keratins (By similarity).
Synonyms: KAP2.3; KRTAP2.3
Tractability: No criterion of Open Targets' tractability assessment is met for any kind of drug.
Gene: Protein-coding gene on chromosome 17 (41,059,240 to 41,060,114, reverse strand). Ensembl gene ENSG00000212724.
Pathways (Reactome):
Developmental Biology: Keratinization
Gene Ontology:
Molecular function: protein binding
Cellular component: cytosol; keratin filament
Genetic constraint (gnomAD): Loss-of-function variants: 9 observed, 7.48 expected, observed/expected ratio (o/e) 1.2, 90% interval 0.71 to 1.85. That is too few expected variants to judge how well the gene tolerates losing a copy. Missense variants: 93 observed, 134.89 expected, observed/expected ratio (o/e) 0.69, 90% interval 0.58 to 0.82. Synonymous variants: 45 observed, 55.77 expected, observed/expected ratio (o/e) 0.81, 90% interval 0.63 to 1.03.
Homologues: Orthologues: mouse Krtap5-24 (43% identical), mouse Krtap5-26 (38% identical), mouse Krtap5-2 (36% identical), rat Krtap5-8 (35% identical), rat AABR07006049.1 (34% identical), mouse Krtap5-20 (33% identical). Paralogues in human: KRTAP2-4 (100% identical), KRTAP2-1 (99% identical), KRTAP2-2 (95% identical), KRTAP4-12 (52% identical), KRTAP4-6 (52% identical), KRTAP4-3 (51% identical), KRTAP4-11 (50% identical), KRTAP4-5 (50% identical), KRTAP4-9 (48% identical), KRTAP4-4 (46% identical), KRTAP9-1 (46% identical), KRTAP10-11 (45% identical), and 35 more.